CDRT15 (CMT1A duplicated region transcript 15)
Tractability: Antibody: the Human Protein Atlas places it where antibodies can reach.
Gene: Protein-coding gene on chromosome 17 (14,235,673 to 14,236,862, reverse strand). Ensembl gene ENSG00000223510.
Subcellular location (Human Protein Atlas): Plasma membrane
Genetic constraint (gnomAD): Loss-of-function variants: 9 observed, 11.68 expected, observed/expected ratio (o/e) 0.77, 90% interval 0.46 to 1.34. The upper end of that interval is the gene's LOEUF score, 1.34, which puts it in group 5 of 6, group 1 being the genes least tolerant of losing a copy. Missense variants: 117 observed, 180.04 expected, observed/expected ratio (o/e) 0.65, 90% interval 0.56 to 0.76. Synonymous variants: 50 observed, 67.58 expected, observed/expected ratio (o/e) 0.74, 90% interval 0.59 to 0.94.
Homologues: Orthologues: macaque CDRT15 (76% identical). Paralogues in human: CDRT15L2 (79% identical).
Diseases named in the same sentence as CDRT15 in open-access papers:
CDRT15 is named in the same sentence as 4 diseases in open-access papers, as found by Europe PMC text mining. Sharing a sentence is not in itself a finding about the gene and the disease.
CDRT15 shares sentences with these, for which no sentence is quoted: autism (1 paper); cardiovascular disease (1); Charcot-Marie-Tooth disease (1); DiGeorge Syndrome (1).